IL4 (interleukin 4)
Diseases named in the same sentence as IL4 in open-access papers (continued):
Sharing a sentence is not in itself a finding about the gene and the disease.
pneumococcal infection (7 papers, 2010 to 2026). Infections with bacteria of the species streptococcus pneumoniae. "IL-4 plays a central role in directing the development of the Th2 phenotype and IL-4 responses in lung have been associated with an increased risk to pneumococcal infection." (PMID 20195541, 2010). "Studies indicate higher IL-4 levels in children with MPP than in those with Streptococcus pneumoniae infection or healthy controls." (PMID 41313182, 2026). "The heightened levels of IFN-γ and IL-4 in BAL and serum samples from the mice treated with Cp 090104 or CP-derived BLPs during pneumococcal infection indicated an enhancement in the activation of Th1 and Th2 cellular immune defenses." (PMID 38675794, 2024). "Here we found a significant up-regulation in BAL and serum Th2-cytokine IL-4 in malnourished mice fed with BCD+PG05 after pneumococcal infection, unlike PG06 or PG534 treatments." (PMID 29518131, 2018). "As expected, the classic type-2 cytokines IL4, IL5, and IL-13 were increased in the lungs of HDM-exposed mice, and pneumococcal infection did not alter their respective levels." (PMID 35273509, 2022).
pulmonary arterial hypertension (7 papers, 2019 to 2024). Pulmonary arterial hypertension (PAH) is a group of diseases characterized by mean pulmonary artery pressure >20 mmHg and elevated pulmonary arterial resistance leading to right heart failure. "Despite all these observations, the role of IL-4 on the remodelling process and pulmonary hypertension is still uncertain and needs further investigation." (PMID 31024947, 2019). "In a hypoxia-induced pulmonary hypertension model, Th2 regulation did not play a role since IL-4 and STAT6-deficient mice had the same HIMF expression levels as wild-type mice." (PMID 33800244, 2021). "With respect to pulmonary arterial hypertension, the effect of IL-5 may be similar to that of IL-4, and the severity of pulmonary arterial muscularization correlates with IL-5–expressing T cells." (PMID 31024947, 2019). "Numerous cytokines elevated in our study, such as IL-1α, IL-4, IL-5,IL-6, IL-7, IL-8, TNF-α were previously shown to involved in VOC-related acute clinical complications such as acute chest syndrome, pulmonary hypertension, and pulmonary thrombosis." (PMID 38361924, 2024). "The roles of IL-4 and STAT6 are also critical to HIMF-mediated pulmonary hypertension." (PMID 33800244, 2021).
renal carcinoma (7 papers, 2016 to 2024). A carcinoma arising from the epithelium of the renal parenchyma or the renal pelvis. "IL-4 expression has been shown to be associated with increased recurrence and reduced survival in renal cancer patients." (PMID 27895317, 2016). "High level of IL-4 expression is associated with increased recurrence and reduced survival in renal carcinoma patients." (PMID 27895317, 2016). "Moreover, the attenuated sphere forming ability of IL4-knockdown cells was accompanied by the downregulation of Sox2 and Oct4, which are known as markers of breast and renal cancer stem cells." (PMID 27895317, 2016). "A recent study showed that preserved eggs induced apoptosis in renal cancer cells by up-regulating the expression of the pro-apoptotic factors Bax and IL-10, and down-regulating the expression of the anti-apoptotic factors interleukin-4 (IL-4) and interleukin-6 (IL-6)." (PMID 36832875, 2023). "In renal cancer, the high expression of FCER1G may be a functional basis for the induction of M2 macrophages by the increased secretion of IL-4." (PMID 36778919, 2023).
acne (6 papers, 2014 to 2025). An inflammatory process of the sebaceous glands which is characterized by comedones, nodules, papules and/or pustules on the skin. "Thus it is hypothesized that IL-4 and IL-4R are involved in the inflammatory processes associated with acne." (PMID 33849530, 2021). "IL-4 expression is increased in acne hypertrophic scars, which is significantly importance for the prognosis of acne vulgaris." (PMID 40230697, 2025). "Further, a Th1 cytokine pattern characterized by high IFN-γ production and low IL-4 production indicated the involvement of Th1 cells in the adaptive immune response in acne vulgaris, particularly in the early stage." (PMID 38193084, 2023). "While the specific roles of IL-4 and IL-4R in the pathogenesis of acne are unclear, these proteins are known to play a role in inflammatory responses." (PMID 33849530, 2021). "However, due to the unclear mechanism of Tanshinone’s effect on IL-4 during the course of acne, these results should be interpreted with caution." (PMID 40230697, 2025). "On the other hand, in fragile populations (i.e., elderly), the presence of oncologic, cardiovascular or allergic comorbidities, recurrent herpes zoster infections, or acne vulgaris could orient the physician toward an anti IL4/13 monoclonal antibody." (PMID 39064029, 2024). "In addition, while the role of SEMA4B in acne pathogenesis is uncertain, it is known to be involved in immune responses and downregulates the secretion of IL-4 and IL-6 in basophils." (PMID 33849530, 2021).
acute pancreatitis (6 papers, 2009 to 2026). An acute inflammatory process that leads to necrosis of the pancreatic parenchyma. "The next interesting finding of our current study is observation that induction of acute pancreatitis by cerulein increases plasma level of interleukin-4 (IL-4) and pretreatment with ghrelin dose-dependently enhances this effect." (PMID 28665321, 2017). "IL-4 reduced necrosis in this model of acute pancreatitis and authors suggested that this effect was related to enhanced expression of complement regulatory proteins, CD55 and CD59." (PMID 28665321, 2017). "We isolated liver macrophages from the rats with acute pancreatitis and the isolated cells were treated by IL-4 or Treg cells." (PMID 25259888, 2014). "Also, it has been stated that proinflammatory cytokines (TNFα, IL-1β, and IL-6) were significantly reduced, whereas antiinflammatory cytokines (IL-10 and IL-4) were increased in animals with acute pancreatitis pretreated with melatonin." (PMID 38333760, 2024). "Too low level of anti-inflammatory IL-4 or too low increase in serum level of this cytokine in response to the presence of pro-inflammatory factors can disturb this balance and lead to the development of acute pancreatitis and/or increase in its severity." (PMID 28665321, 2017). "Anti-inflammatory effect of IL-4 was also found in acute pancreatitis." (PMID 28665321, 2017). "In addition, clinical studies indicate that IL-4 affects the development and course of acute pancreatitis." (PMID 28665321, 2017). "Ablation of sensory nerves by neurotoxic doses of capsaicin performed before induction of acute pancreatitis significantly reduced plasma concentration of anti-inflammatory IL-4 and showed a tendency to an additional increase in pancreatic weight and decrease in pancreatic blood flow." (PMID 28665321, 2017). "Our results indicate that peritoneal macrophages adopt a pro-inflammatory activation early during acute pancreatitis and that they could be reprogrammed in vitro to a reparative M2 phenotype by IL-4 and IL-13." (PMID 19646232, 2009). "We evaluated the activation phenotype in peritoneal macrophages during the progression of an experimental model of acute pancreatitis induced in rats by intraductal administration of 5% sodium taurocholate and the effect of IL-4 and IL-13 to modulate this activation." (PMID 19646232, 2009). "Acute pancreatitis, as well as endoscopic retrograde cholangiopancreatography (ERCP) increases serum level of interleukin-4." (PMID 28665321, 2017). "On the other hand, ghrelin did not affect plasma level of IL-4 in rats without induction of acute pancreatitis." (PMID 28665321, 2017). "Administration of ghrelin was also without any effect on plasma concentration of interleukin-4 in rats with CDSN without induction of acute pancreatitis." (PMID 28665321, 2017). "Fortunately, our present study also showed that ghrelin does not affect plasma level of interleukin-4 in rats without induction of acute pancreatitis." (PMID 28665321, 2017). "DCQD treatment could increase the expression of anti-inflammatory cytokines (IL-4 and IL-10) and inhibit the expression of proinflammatory cytokines (TNF-α and IL-6) to ameliorate the histopathological damage of acute pancreatitis, in which higher dose DCQD seems to have the better effect." (PMID 26199633, 2015). "In rats with ablation of sensory nerves before induction of acute pancreatitis, pretreatment with ghrelin was without any effect on morphological signs of pancreatic damage, pancreatic weight, plasma level of pancreatic digestive enzyme, lipase or plasma concentration of TNF-α and IL-4." (PMID 28665321, 2017).
aneurysm (6 papers, 2009 to 2025). Bulging or ballooning in an area of an artery secondary to arterial wall weakening. "Experimental models suggest that IL-4 produced by eosinophils may protect against the development of aneurysms." (PMID 38055674, 2023). "Finally, it would be interesting to evaluate if levels of circulating IgEs, tryptase, or IL-4 correlate with aneurysm growth in a longitudinal study, and therefore be used as markers for AAA progression." (PMID 38055674, 2023). "Clinical and experimental studies carried out in abdominal aortic aneurysms byhistological and immunohistochemical procedures proved that a predominantTh2-mediated immune response, mainly driven by IL-4, IL-5, or IL-10 cytokines,induces severe aneurysm formations." (PMID 30810667, 2019). "However, our data suggest that IL-4 may accelerate the rupture of established aneurysms." (PMID 38055674, 2023). "Blockade of IFN-γ action results in IL-4 driven inflammation, directly increases expression of MMP-9 and -12 leading to aneurysm formation." (PMID 24358274, 2013). "By contrast, IL‐4 is typically anti‐inflammatory, and its reduced level in AAA EVs may reflect the shift toward a pro‐inflammatory environment within the aneurysm." (PMID 40770945, 2025).
autoimmune hepatitis (6 papers, 2014 to 2024). Hepatitis caused by autoantibodies. "Here, we show suppressive effects of dopamine on IL4 and IFNγ production from hepatic iNKT cells, and demonstrate a protective role of dopamine in inhibiting iNKT cell-mediated autoimmune hepatitis." (PMID 30386344, 2018). "Recently, studies have reported that Con A-induced autoimmune hepatitis is largely mediated by the release of inflammatory cytokines such as IL-2, IL-4, IL-6, IL-10, IL-12, TNF-α and IFN-γ." (PMID 24498418, 2014). "Perhaps IL-4 could play a role in drug-induced autoimmune hepatitis, opening a window to develop more personalized approaches to the treatment of AIH subtypes." (PMID 41585412, 2024).
brain tumor (6 papers, 2007 to 2025). "IL-4 treatment is reported to promote the polarization of microglia towards a tumor-supportive phenotype that is observed in the context of brain tumors." (PMID 34082793, 2021). "Previously, we have demonstrated overexpression of interleukin 4 (IL-4) and IL-13 receptors on adult and pediatric brain tumors and meningiomas." (PMID 30572904, 2018). "Due to the overexpression of IL-4 receptor in glioma cell lines and primary specimens compared to the normal brain tissues, it was proposed that IL-4 can serve as a cytotoxic treatment in brain tumor therapy." (PMID 28346397, 2017). "Although our analyses of IL-4 tumor vaccine models have led us to understand the critical roles of type-1 immunity for brain tumor immunotherapy, effective type-1 immunity may also be achieved by clinically more feasible modalities than IL-4 transfected fibroblasts." (PMID 18093335, 2007). "ROC analysis of immunological molecules in serum and CSF showed that the expression levels of IL-4, IFN-α, IFN-γ, IL-6, TNF-α, CCL4, CCL11, and VEGF exhibited high sensitivity and specificity in distinguishing between brain inflammation and brain tumor groups (p < 0.05)." (PMID 39364412, 2024).
cerebral infarction (6 papers, 2016 to 2025). An ischemic condition of the brain, producing a persistent focal neurological deficit in the area of distribution of the cerebral arteries. "In human postmortem brain tissue samples, IL-10, IL-4, and their receptors co-localize with reactive astrocytes in active demyelinating MS lesions, as well as in areas of brain infarction." (PMID 36231129, 2022). "Elevated IL-4 level in the human serum may be an important factor in cerebral infarction during the acute stage." (PMID 27679860, 2016). "2ME2 and IL-4+2ME2 groups had decreased NDS, cerebral infarction volume, brain water content, apoptosis rate and MDA, ROS, HIF-1α, BNIP3, LC3-II and Beclin-1 levels, but increased SOD level compared with those of IL-4 group (P<0.05)." (PMID 36910409, 2022). "Compared with IR group, NDS, cerebral infarction volume, brain water content, apoptosis rate, and MDA and ROS levels decreased, while SOD, HIF-1α, BNIP3, LC3-II and Beclin-1 levels increased in IL-4 group (P<0.05)." (PMID 36910409, 2022).
chronic bronchitis (6 papers, 2021 to 2025). A type of chronic obstructive pulmonary disease characterized by chronic inflammation in the bronchial tree that results in edema, mucus production, obstruction, and reduced airflow to and from the lung alveoli. "Exacerbations of chronic bronchitis are often accompanied by significant airway eosinophilia, characterized by the release of inflammatory mediators including interleukin-4 (IL-4), interleukin-5 (IL-5), and interleukin-13 (IL-13)." (PMID 39361621, 2024). "Also, an increased proportion of cells expressing IL4 and IL13 has been found in smokers with chronic bronchitis compared to asymptomatic smokers." (PMID 40468357, 2025). "Additionally, smokers without chronic obstructive bronchitis exhibit plasma cells that express IL-4 and IL-5, with IL-4 promoting mucus secretion and exacerbating lung inflammation." (PMID 40997602, 2025).
chronic hepatitis C (6 papers, 2012 to 2021). "In contrast, the levels of IFN-γ were described to be lower in another population of chronic hepatitis C patients compared to controls, while IL-4 and IL-10 were higher." (PMID 29977152, 2018). "In another study, chronic hepatitis C patients presented elevated serum levels of IL-10, IFN-γ, IL-6, and IL-4, while IL-1, IL-2, IL17, IL-22, IL-13 TNF, IL-12p70, and IL-15 levels were lower in patients compared to healthy controls." (PMID 29977152, 2018). "Another study found that liver-infiltrating T cells from chronic hepatitis C patients produced IFN-γ but not IL-4 or IL-5, while T cells from chronic hepatitis B patients were able to produce IFN-γ, IL-4, and IL-515." (PMID 28928388, 2017).
cystic fibrosis (6 papers, 2010 to 2025). Autosomal recessive disorder caused by pathogenic variants in the CFTR gene (cystic fibrosis transmembrane conductance regulator), which encodes a chloride and bicarbonate channel expressed in epithelial cells, and follow the diagnosis criteria. "Low INF-γ levels and tendency to increased IL-4 levels were found in the group with cystic fibrosis." (PMID 20339685, 2010). "Chronic P. aeruginosa biofilm infections in cystic fibrosis patients are dominated by a Th2 response with increased and decreased levels of IL4 and IFNγ, respectively, suggesting that P. aeruginosa biofilms persist by reducing host proinflammatory responses to infection." (PMID 32903626, 2020). "Therefore, this study aims to analyze the expression of messenger ribonucleic acid (mRNA) for IL-4, IL-5, IL-6, IL-8, GM-CSF, and INF-γ in patients with cystic fibrosis and control subjects through reverse transcription polymerase chain reaction (RT-PCR)." (PMID 20339685, 2010).
cysticercosis (6 papers, 2011 to 2025). "This Th2 polarized response is likely to be the cause of the reprogramming of Ly6Chi recruited monocytes into AAMφs during experimental cysticercosis since IL-4 enhances most of the up-regulated genes observed in this study." (PMID 28094319, 2017). "Importantly, our study points to the potential influence of sex in modulating cytokine profiles in response to cysticercosis and HIV, with male sex being associated with decreased levels of IL-8, IL-17, IL-4, and ICAM-1, emphasizing a suppressive effect of male sex on these cytokines." (PMID 39093864, 2024). "In early stages of experimental cysticercosis a clear but transient Th1-type immune response develops (high levels of IL-2 and IFN-γ), but as infection time progresses a permanent Th2-type response follows (high levels of IL-4, IL-6 and IL-10)." (PMID 21912714, 2011). "This could be the cause of the observed immune response that was not fully in accordance with more recent correlates of cysticercosis protection, including low levels of IgG together with high levels of IL-4." (PMID 40563507, 2025). "The immunopathology of T. crassiceps cysticercosis in mice is that of an initial non-permissive Th1 type, which shifts to a parasite permissive Th2 type during chronic stage of infection and is accompanied by an increase in IL-4, IL-6 and IL-10 cytokines." (PMID 22206032, 2011).
echinococcosis (6 papers, 2015 to 2025). A parasitic infection caused by tapeworm larvae of Echinococcus. "Clinical data on the effects of ABZ in echinococcosis patients revealed significant reductions in IL-10 and partial reductions in IL-4 in serum that was associated with the successful therapy." (PMID 40725240, 2025). "Interestingly, unlike the type of T cell response generated in chronic patients with echinococcosis, we found that primed splenocytes with HF-stimulated BMDCs blocked the induction of cytokines related to Th2 profile (il-4, il5, il-13)." (PMID 38817444, 2024). "Anti-echinococcosis-related cytokines (IL-2, IL-4, IL-10) were significantly increased." (PMID 34488852, 2021).
enteritis (6 papers, 2017 to 2025). Inflammation of the small intestine. "These cause activation of lymphocytes to secrete pro-inflammatory cytokines such as interferon-γ, interleukin-4, and tumor necrosis factor-α, causing damage to the villi and resulting in enteritis." (PMID 32617423, 2020). "External GABA administration enhances gut microbiota diversity and mitigates ETEC-induced enteritis in piglets by boosting the secretion of sIgA and the anti-inflammatory cytokine IL-4 within the jejunum tissue." (PMID 39334800, 2024). "In addition, we investigated the change in the proportion of Th2 cytokines in the intestinal mucosa of mice with DSS‐induced enteritis using ELISA, finding that the mice with DSS‐induced enteritis displayed significantly higher IL‐4, IL‐5 and IL‐13 levels than the control group." (PMID 33569850, 2021). "In the present study, TS1 also reduced the SE-induced increase in the expression of pro-inflammatory cytokines (IL-1β, IL-6, TNF-α, IL-4, MCP-1) in the intestine and serum, which is consistent with previous findings and observations of lipopolysaccharide-induced enteritis in vitro." (PMID 36759839, 2023). "High percentage of dietary SBM could induce enteritis in L. crocea, showing increased proinflammatory cytokine production (IL-1β, IL-6, and TNF-α) and decreased anti-inflammatory cytokine expression (IL-4/13a, IL-4/13b, and TGF-β)." (PMID 40688731, 2025).
esophageal squamous cell carcinoma (6 papers, 2020 to 2025). Esophageal squamous cell carcinoma (ESCC) is a type of esophageal carcinoma (EC) that can affect any part of the esophagus, but is usually located in the upper or middle third. "The present study recruited 721 esophageal squamous cell carcinoma (ESCC) cases and 1208 controls and explored the roles of single nucleotide polymorphisms (SNPs) in the interleukin-4 (IL-4), IL-10, and herpesvirus entry mediator (HVEM) genes in contributing to ESCC risk." (PMID 32744314, 2020).